TLR2 (toll like receptor 2)
Diseases named in the same sentence as TLR2 in open-access papers (continued):
Sharing a sentence is not in itself a finding about the gene and the disease.
tumor (continued). "In lung cancer, silencing TLR2, TLR4, and TLR9, along with epithelial-specific MyD88/NF-κB signaling, significantly reduces the expression of pro-tumor immunosuppressive factors like RETNLB, while enhancing the expression of anti-tumor cytokines like IFN-γ." (PMID 41200171, 2025). "Subsequently, western blot and ELISA analyses were conducted on splenic CD11b+ cells from non‐lymphoid layers of normal mice, TLR2‐/‐ mice, and IRF7‐/‐ mice following KK2DP7 training and subsequent tumor or LPS inoculation for 48 h." (PMID 40145812, 2025). "TLR2 and TLR4 are overexpressed in many tumor types and act as proto-oncogenes by affecting tumor cell proliferation, migration, and metastasis." (PMID 40809181, 2025). "In mouse tumor models, research has demonstrated that adding adjuvants such as PAM3CSK4, a TLR2 and TLR1 agonist, to LNPs enhances humoral immunity, cellular responses, tumor inhibition, and survival rates." (PMID 40589473, 2025). "In TLR2‐/‐ and IRF7‐/‐ mice, the anti‐tumor efficacy and interferon secretion induced by KK2DP7‐mediated training immunity were significantly reduced." (PMID 40145812, 2025). "Some TLR signals also contribute to tumor progression, and HBsAg can increase the invasiveness of HBV‐induced HCC cells by enhancing TLR2 transcription." (PMID 40727252, 2025). "For instance, in brain cancers like glioma, activation of TLR2, TLR4, and TLR9 promotes tumor growth and metastasis by modulating signaling pathways such as NF‐κB and MAPK." (PMID 40922674, 2025). "Activates TAM polarization to M1 phenotype via TLR2; induces CD8+ T cell response; promotes tumor apoptosis via iron deprivation." (PMID 41181090, 2025). "Canonical NF-κB signaling, triggered by pathways such as TLR2/4-MyD88 and TNFR/TNFR2, enhances MDSC immunosuppression by increasing IL-10 and TGF-β production, thereby dampening T-cell responses and fostering tumor progression." (PMID 40562870, 2025). "Further supporting a role for Hsp70, TLR2, and MerTK, the tumors from Hsp70 KD LLC-GFP and LN229 cells, and LLC-GFP tumors from TLR2 null mice showed impaired MΦ polarization and tumor growth." (PMID 39941817, 2025). "In breast cancer cells, activation of TLR2 and TLR4 stimulates NF-κB, regulating the secretion of cytokines such as IL-6, TGF-β, VEGF, and MMP9, promoting tumor invasion, migration, and progression." (PMID 41200171, 2025). "In 4T1 tumours treated with SFV/IFNγ and TLR2/1 ligand Pam3SCK4, the amount of CTLs was increased and the amount of Tregs was significantly reduced." (PMID 40547518, 2025). "HMGB1 seeks binding targets in the TME such as RAGE on tumour cells or RAGE on immune cells and TLR2/4 binding." (PMID 38652105, 2024). "In hepatic stellate cells, DCA induces the SASP, turning in the secretion of inflammatory and tumor-promoting factors in the liver and the overexpression of COX-2 and its downstream inflammatory cascade, together with TLR-2-mediated signaling." (PMID 39064815, 2024). "In addition, tumor immune evasion could result from activation of TLR2-mediated signaling pathways." (PMID 39164536, 2024). "IFN-γ modulates TLR2-induced signaling by suppressing MAPK activation and recruits and activates immune cells in the tumor microenvironment." (PMID 39408882, 2024). "In summary, we demonstrate a connection between TGF-β, IL-6, TLR-2 and TLR-4 expression by the primary CRC tumor to SPP1 and FN1 expression in the metastatic intrahepatic tumor." (PMID 39372792, 2024). "TLR2 is expressed on keratinocytes of OTSCC and specifically regulates the growth and survival of tumor cells by promoting immune escape and inhibiting apoptosis." (PMID 39403369, 2024).
tumor (continued). "Research on TLR2 expression in CRC is burgeoning, underscoring its crucial impact on tumor progression, the immune response, and patient outcomes." (PMID 38979413, 2024). "The activation of TLR-2 and TLR-9 by PCa cells appears to promote tumour growth; conversely, the activation of TLR-3, TLR-5, and TLR-7 has been suggested as a potential way to prevent PCa." (PMID 39201739, 2024). "In such cases, TLR inhibitors such as OPN-301 (anti-TLR2) and other TLR7/9 inhibitors have shown the potential to inhibit tumor growth in preclinical models." (PMID 39451226, 2024). "In gastric cancer (GC), TLR2, TLR3, TLR4, and TLR9 are crucial for modulating immune response and tumor progression." (PMID 39451226, 2024). "For example, HSP72 and HSP105 on the surface of tumor exosomes can promote tumor metastasis by inducing IL-4 secretion from DCs in a TLR6 and TLR2-dependent manner." (PMID 38633106, 2024). "S. gastrop (P. anaerobius) has been shown to interact with TLR2 and TLR4 on colon cells to regulate a variety of immune cells including MDSCs, TAMs, and granulocyte tumor‐related neutrophils, thus promoting colon carcinogenesis." (PMID 36860568, 2023). "We found that TLR2 inhibition reduced the number of DCN+ macrophages in tumor and attenuated tumor suppressive effect of B.adolescentis-treated macrophages." (PMID 37464382, 2023). "We found that the Arf1‐ablated tumor cells release oxLDL, HMGB1‐gDNA complex, and also induce expression of CD36, TLR2, and TLR6 in DCs." (PMID 37786300, 2023). "Other proteins that also showed increased expression in tumor tissue are Protein Tyrosine Phosphatase Receptor Type C (PTPRC) and Toll-Like Receptor 2 (TLR2)." (PMID 36615183, 2023). "LMW-HA induces the secretion of inflammatory factors, matrix hydrolases and pro-angiogenic factors by activating the specific receptors such as TLR2, TLR4, and LAYN of tumor cells, which dominates in the field of metastasis and colonization." (PMID 36698043, 2023). "According to the current studies, there are 7 HA receptors, CD44, RHAMM, TLR2, TLR4, LYVE, LAYN and STAB2, which participate in connecting extracellular signal and intracellular signalling in tumor diseases." (PMID 36698043, 2023). "With a few notable exceptions, stimulation of TLR1, TLR2 and TLR4 often leads to tumor-promoting effects by inducing immunosuppressive and antiapoptotic signals." (PMID 37112730, 2023). "TLR2, TLR4, and inflammasome inducing MR, NLRP3 can lead to tumor progression via the production of inflammatory cytokines (IL6, IL16), increased cell proliferation, and resistance to apoptosis (TNFAIP3)." (PMID 37599366, 2023). "The CD36/TLR2/TLR6 form a coreceptors complex on DC surface, and the exogenous ligands of tumor‐derived oxLDL and HMGB1‐gDNA complex join the coreceptors complex through binding CD36 and TLR2/TLR6, respectively." (PMID 37786300, 2023). "Finally, we investigated whether YTHDF1 maintained HPSCC tumor progression via TLR2." (PMID 37612282, 2023). "It is a potent TLR2 and TLR9 ligand and mediates anti-tumor immune responses in MyD88 dependent pathway." (PMID 37122749, 2023). "Our results showed that IL-6, IL-17, TNF-α, TLR-2 and TLR-4 genes were overexpressed in tumor tissues compared to adjacent normal tissues." (PMID 38075864, 2023). "To further investigate the clinical relevance, we quantified B.adolescentis and the expression of TLR2 and DCN with quantitative qRT-PCR analysis in paired fresh CRC and adjacent non-tumor tissue." (PMID 37464382, 2023). "Subsequently, we attempted to perform immunohistochemistry (IHC) staining for NRGs (CYBB, ITGB2, ITGAM, LILRB2, TLR2, and TLR7) in kidney sections from ANCA-GN patients and age- and sex-matched ccRCC patients with adjacent non-tumor tissues." (PMID 37465687, 2023). "Out of 21 ICD-related genes with notably different expressions, seven genes, namely ROCK1, BCL2, TLR2, TLR9, AGER, CASR, and P2RX7, were found to have decreased expression in tumor samples, while the rest were upregulated." (PMID 37932362, 2023).
tumor (continued). "They find that the Arf1‐ablated tumor cells release OxLDL, HMGB1, and genomic DNA, which together bound to a coreceptor complex of CD36/TLR2/TLR6 on DC surface." (PMID 37786300, 2023). "A more interesting study on colon cancer found that an important DAMP molecule released by dying tumor cells, translational control tumor protein (TCTP), activates TLR2 on M-MDSCs and promotes the secretion of CXCL1/2, recruiting PMN-MDSCs into the TME." (PMID 36911674, 2023). "Among all TLR2, TLR4, and TLR5 subgroups and the positive TLR7 subgroup, patients with a low CD3–CD8 tumor–stroma index exhibited a worse survival." (PMID 36649244, 2023). "Li and colleagues found that the molecule Pam3CSK4, an agonist of Toll-like receptor 2 (TLR2), injected into mice inhibited tumour growth and reduced myeloid-derived suppressor cells (MDSCs), thereby attenuating HCC progression." (PMID 37759525, 2023). "TLR2 signaling upregulated microglia-derived MMP14 and MMP9 production, which accelerate ECM degradation and reorganization and induce tumor cells to move and invade." (PMID 35920986, 2022). "Regarding antitumor therapy, CpG in conjunction with an anti-TLR2 antibody have been shown to induce the production of IFNγ and the migration of CD8 T and NK lymphocytes to the tumor stroma." (PMID 36365602, 2022). "Actinomyces induces activation of the TLR2/NF-κB and TLR4/NF-κB pathways to promote inflammation and suppress anti-tumor responses by inhibiting the infiltration of CD8+ T lymphocytes." (PMID 36119074, 2022). "We measured TLR9, 2 and 4 expressions in our tumor samples and classified our cohort of patients as showing high (≥2) or low (<2) score expression levels of TLR9 (n=22), TLR2 (n=28) and TLR4 (n=29)." (PMID 35990685, 2022). "TLR2/TLR9 activation has also been shown to enhance DC maturation, which is essential for the effective processing and presentation of tumor antigens on MHC molecules." (PMID 35740589, 2022). "Recent studies have shown that UV-oHSV2 can stimulate NK cells to secrete IFN-γ, which is achieved through the Toll-like receptor 2 (TLR2)/NF-κB signaling pathway, which activates multiple immune cells to exert anti-tumor responses." (PMID 36090998, 2022). "To do this, we analyzed the methylation patterns of the TLR2 locus in LUAD and LUSC tumor samples from the TCGA and compared them with adjacent normal lung tissue." (PMID 36351380, 2022). "Nonetheless, these data strongly suggest a potential tumor suppressor function of TLR2 in NSCLC and suggest a common role of TLR2 in NSCLC subtypes." (PMID 36351380, 2022). "Many HPS are rich in galactose and mannose structural units and can specifically recognize the highly expressed asialoglycoprotein receptor (ASGPR) and CD44 receptor in tumor cells, as well as MRs, CD206, and TLR-2 in tumor-related macrophages." (PMID 36015329, 2022). "Actinomyces triggers the expression of several microbial- and immune-related genes, including TLR2, TLR4, and NF-κB, which promote CRC development by regulating inflammation and anti-tumor immunity." (PMID 36119074, 2022). "TLR2 and TLR4 in a double knockout metastatic lung cancer model have been shown to influence the ability of the tumor to proliferate and grow, as well as to decrease the number of neutrophils associated with the tumor." (PMID 36389785, 2022). "TLR2 and TLR 7/8 are highly expressed in monocytic-MDSCs (m-MDSCs) making them an important aid for tumor immune evasion." (PMID 36389785, 2022). "Injured tumor cells express or release DAMPs, in which HSP70 bound to intracellular tumor-specific antigen is released to TLR2 and TLR4 on the surface of extracellular binding DCs to promote TLR maturation and movement to lymph nodes." (PMID 36355531, 2022). "This suggest that in the cross-talk between microglia and tumor cells, there is a MMP9-promoting pathway complementary to TLR2." (PMID 35992852, 2022).
tumor (continued). "LP simultaneously activated TLR2 and TLR3 signaling, thereby extensively changing the immune-related gene signatures within the tumor microenvironment (TME)." (PMID 35764365, 2022). "Differential analysis showed that GNAI3, PCDH7, PSEN1 and TNFSF9 were highly expressed in tumor tissues, while ADM, CD69, SLC11A2 and TLR2 were opposite." (PMID 36117156, 2022). "In this work, we demonstrate that some components from the T. cruzi lysate have anti-tumour properties and can trigger mouse and human TLR4 and human TLR2." (PMID 36499361, 2022). "Here, we demonstrated that LP, a potent TLR2 and TLR3 agonist, can remodel the tumor immune microenvironment and enhance antitumor immunity." (PMID 35764365, 2022). "We then evaluated the expressions of all TLRs in KIRC tumor tissues by GEPIA and found that TLR3 was particularly highly expressed in KIRC, followed by TLR4 and TLR2, which was consistent with the results of UALCAN database." (PMID 35127830, 2022). "Previous studies have shown that multiple PRRs (TLR2, TLR3, TLR4, TLR7, TLR8 and RIG‐1) in stromal cells recognise tumour cell‐derived EVs and participate in tumour metastasis." (PMID 36068649, 2022). "Herein, we decided to investigate the role of four different MyD88-dependent single TLRs (TLR2−/−, TLR4−/−, TLR7−/− and TLR9−/−) in BCG tumor treatment." (PMID 34341449, 2021). "There was a significant delay in tumor growth with reduced tumor incidence and weight in DKO mice versus WT, while single Tlr2–/– and Tlr4–/– mice presented an intermediate phenotype." (PMID 34032639, 2021). "Previous reports indicate that tumor cells express RAGE, TLR-2, and TLR-4 to promote HMGB1-induced tumor growth." (PMID 34966671, 2021). "For instance, HSPA1A promotes hepatoma cell proliferation through TLR2 and TLR4 signaling pathways, and HSPA1L/HIF-1 α/GP78 significantly influences tumor progression." (PMID 34059060, 2021). "M1 macrophages are characterized by the expression of Toll-like receptors (TLRs) and opsonic receptors (e.g., TLR2/4, CD16, CD32, CD64), the production of pro-inflammatory mediators and exhibit a strong anti-tumor activity." (PMID 33924378, 2021). "Versican stimulation of TLR2 on macrophages increases the expression of TNF-α, which can sometimes promote tumour progression through mechanisms such as PD-L1 upregulation on both myeloid and tumour cells." (PMID 34527586, 2021). "The main mechanism of biglycan signaling employs TLR2 and TLR4 receptors and results in pro-tumorigenic effects, including the production of cytokines and growth factors that ultimately promote tumor angiogenesis." (PMID 34917515, 2021). "MMP2-expressing cells were found proximal to CD45+ cells, suggesting an interaction between hematopoietic cells that express TLR2 and -4 and MMP2+ tumor or stromal cells." (PMID 34032639, 2021). "Some studies have shown that HSPA1A can enhance the apoptosis resistance of H22 cells to promote tumor growth by activating NF- κB, and HSPA1A of extracellular to the endogenous ligand of TLR4 and TLR2." (PMID 34059060, 2021). "Here, we show that, in response to TLR2 stimulation, BE organoids and early-stage EAC cells secrete pro-inflammatory cytokines and chemokines which recruit macrophages to the tumour site." (PMID 33922955, 2021). "Both in vitro and in vivo experiments have shown that TLR2 and TLR5 were highly expressed in tumor-infiltrating microglia and possessed antitumor activity." (PMID 34715891, 2021). "In KIRC, the results suggested that the mRNA levels of TLR1, TLR2, TLR3, TLR4, TLR7, and TLR8 were elevated in tumour tissues compared with normal kidney tissues." (PMID 34531911, 2021). "Due to the ability of biglycan to affect ROS production via TLR2 and TLR4 in a NOX1- and NOX4-dependent manner, it is very likely that biglycan potentially influences tumor angiogenesis via ROS level regulation." (PMID 34917515, 2021).
tumor (continued). "Significant down-regulations of TLR2 and TLR7 mRNA were found in both peripheral and tumor-infiltrating CD8+ T cells from GC patients." (PMID 34620075, 2021). "The percentage of TLR2+ cells within CD3+CD8+ T cells in peripheral bloods (31.67 ± 8.84%) and tumor residency (24.37 ± 2.72%) of GC patients was notably lower than in peripheral bloods of NCs (50.96 ± 5.45%) (LSD-t tests, P < 0.0001)." (PMID 34620075, 2021). "Further experiments were also needed to confirm the TLR2 regulation to CD8+ T cells in vivo and to analyze the tumor antigen specific CD8+ T cell response to TLR2 activation in the pathogenesis of GC." (PMID 34620075, 2021). "We evaluate BCG intratumoral treatment in a subcutaneous MB49 tumor model using different knockout (KO) mice (STING−/−, cGAS−/−, TLR2−/−, TLR3−/−, TLR4−/−, TLR7−/−, TLR9−/−, TLR3/7/9−/−, MyD88−/−, IL-1R−/−, Caspase1/11−/−, Gasdermin-D−/− and IFNAR−/−)." (PMID 34341449, 2021). "Another TLR2 agonist is protein-bound polysaccharide-K (PSK) that has been shown to enhance apoptosis and inhibit tumor growth in human PDAC cell lines." (PMID 34884547, 2021). "Despite their protumor activity, TLR2 and TLR4 have been studied as components of adjuvants for vaccination and tumor therapy." (PMID 32012718, 2020). "Our study demonstrates that knocking out the TLR2 gene inhibits CAC growth, reduces tumor severity, and reduces tumor proliferation and that TLR2 is highly expressed in CAC, consistent with the reported effects of TLR2 on tumors." (PMID 32256204, 2020). "The results suggest that knocking out the TLR2 gene can reduce the CAC pathological score and reduce the severity of the tumor." (PMID 32256204, 2020). "We hypothesize that the ability of xCT immunotargeting to inhibit the HMGB1/TLR2 axis may contribute to its therapeutic activity and suggest that it would be worth developing combined therapies targeting these two mechanisms responsible for tumor survival and progression." (PMID 33321934, 2020). "In our previous study, a TLR2 agonist recombinant lipoprotein combined with the TLR9 agonist CpG oligonucleotide (CpG ODN) could dramatically enhance antitumor efficacy and reduce the number of tumor-associated macrophages (TAMs) and myeloid-derived suppressor cells (MDSCs)." (PMID 32231003, 2020). "During the early stage of oral tongue squamous cell carcinoma, TLR2 and TLR4 expressions serve as predictive markers of invasive tumor growth and a higher tumor grade." (PMID 32424768, 2020). "The dichotomous role played by the innate immune system in cancer is exemplified by the ambivalent activity that PRRs, and in particular Toll-like receptor 2 (TLR2), exert in tumor progression." (PMID 33321934, 2020). "Based on the intersection of SAA receptors and TLR superfamily signature between human BC tissues and cell lines to exclude the tumor heterogeneity, TLR1 and TLR2 were highly expressed in both TNBC tissues and cell lines." (PMID 30728901, 2019). "We observed that MIP induced significant tumor regression in TLR4−/− mice, but its antitumor efficacy was substantially reduced in TLR2−/− mice." (PMID 31590685, 2019). "In our whole population-based study of NPC in Finland, we examined the expression of TLR1, TLR2, TLR4, TLR5, TLR7, and TLR9 in 150 tumours and analysed their pattern of expression according to EBV and HPV status, and clinical outcome." (PMID 31238894, 2019). "Alternatively, stimulating TLR2 and TLR4 signaling can promote an anti-tumor immune response in OC models in combination with platinum therapy." (PMID 31443240, 2019). "This study builds upon our previous observations and demonstrates the importance of TLR2 and MyD88 in MIP-mediated tumor regression." (PMID 31590685, 2019). "In Kaposi’s sarcoma, known to be induced by herpes 8 virus, marked reduction of TLR2 and TLR4 was found in tumor cells, what resulted in downregulation of pro-inflammatory cytokine response." (PMID 30976817, 2019).